NDRG1 (N-myc downstream regulated 1)
Diseases named in the same sentence as NDRG1 in open-access papers (continued):
Sharing a sentence is not in itself a finding about the gene and the disease.
bladder cancer (continued). "The immunoscore of the NDRG1 protein in bladder cancer tissues was higher than that in tumour-free tissues (p = 0.000256), and the immunoscore in MIBC patients was significantly higher than that in NMIBC patients (p = 0.0211)." (PMID 30914736, 2019). "Further, mice injected with NDRG1 over-expressing EJ bladder cancer cells exhibited smaller tumors compared to those injected with control EJ bladder cancer cells." (PMID 26431493, 2015). "The results of our study indicate that IL6 upregulated the expression of NDRG1 in bladder carcinoma cells." (PMID 23762858, 2013). "Existing studies mainly support the oncogenic role of miR-145 in urological tumours, but a few evidences suggest that it may exert a pro-tumourigenic function in the metastatic stage of bladder cancer by down-regulating targets such as NDRG1." (PMID 40689207, 2025). "Interestingly, a recent study reported that NDRG1 over-expression promoted EMT in bladder cancer through up-regulation of EMT-related transcription factors including Twist1 and Snail2." (PMID 38561462, 2024). "Our previous studies also demonstrated that CAPE represses the growth of oral squamous carcinoma cells (OSCCs), nasopharyngeal cancer (NPC), and bladder carcinoma cells (BCCs) by activating the MAPK signaling pathway to induce the expression of N-myc downstream regulated 1 (NDRG1)." (PMID 35053438, 2022). "Moreover, our early report demonstrated that GDF15 is the upstream gene of two antitumor genes, NDRG1 and maspin, in bladder carcinoma cells." (PMID 35884930, 2022). "Also, several studies have suggested that NDRG1 is a tumor suppressor gene in bladder carcinoma cells." (PMID 34662721, 2022). "The ROC curve demonstrated that the protein level of NDRG1 could distinguish bladder cancer patients from healthy controls." (PMID 30914736, 2019). "NDRG1 expression in urine from bladder cancer patients was examined by ELISA." (PMID 30914736, 2019). "NDRG1 promoted EMT in bladder cancer and could be an effective diagnostic and prognostic biomarker in bladder cancer patients." (PMID 30914736, 2019). "In addition, our in vitro experimental data showed that NDRG1-modulated bladder cancer cells grew faster via the promotion of proliferation and inhibition of apoptosis." (PMID 30914736, 2019). "Additionally, we stained the Transwell filters with crystal violet after cell culture (48 h for 5637 cells and 24 h for T24 cells) and found that NDRG1 noticeably affected the invasion of bladder cancer cells in vitro (p < 0.01)." (PMID 30914736, 2019). "Moreover, multivariate Cox regression analysis showed that the level of NDRG1 expression was an independent prognostic factor in bladder cancer patients (B = 1.070; p = 0.012; RR (95% CI), 2.916 (1.264–6.724))." (PMID 30914736, 2019). "An NDRG1 overexpression plasmid and NDRG1 siRNAs were transfected into bladder cancer cell lines." (PMID 30914736, 2019). "Therefore, we sought to investigate the expression and function of NDRG1 in bladder cancer and further reveal the ways in which it is involved in EMT." (PMID 30914736, 2019). "We found that urine NDRG1 could be a promising biomarker for the diagnosis of bladder cancer, with an AUC of 0.909 (95% CI, 0.829–0.989), an acceptable sensitivity of 84.6% and a specificity of 86.7%." (PMID 30914736, 2019). "Taken together, these results showed that NDRG1 mediated the invasive bladder cancer phenotype." (PMID 30914736, 2019). "In addition, in bladder cancer, NDRG1 was mainly highly expressed in the cytoplasm (62%) and on the cell membrane (38%), but nuclear staining also existed." (PMID 30914736, 2019). "Although the function and expression of NDRG family genes with regard to bladder carcinoma cells remain poorly understood, our previous report has indicated that NDRG1 is upregulated by interleukin 6, which blocks cell proliferation and invasion in bladder carcinoma cells." (PMID 26249737, 2015).
bladder cancer (continued). "Meanwhile, the results illustrated that GDF15 modulates epithelial-mesenchymal transition (EMT) markers NDRG1, and maspin to suppress the cellular proliferation, invasion, and growth of bladder carcinoma cells in vitro and in vivo, and is defined as an antitumor marker of bladder cancer." (PMID 35884930, 2022). "However, NDRG1 exerts contradictory effects depending primarily on the tissue type affected; whether it acts as a tumour promoter or suppressor in bladder cancer remains to be further elucidated." (PMID 30914736, 2019). "However, the role of NDRG1 in bladder cancer has remained unclear." (PMID 23762858, 2013). "Overall, CAPE upregulates multiple MAPK signaling pathways in bladder carcinoma cells as in OSCC and NPC cells, but the modulation of CAPE in expressions of NDRG1, maspin, and GDF15 occurs via different signals and is cell-dependent." (PMID 34662721, 2022). "To assess the antagonistic effect of CAPE on TGFβ treatments in bladder carcinoma cells, we treated HT1376 cells with CAPE and/or rhTGFβ to determine the expressions of GDF15, maspin, and NDRG1." (PMID 35884930, 2022). "Previously, GDF15 has been shown to modulate the gene expressions of NDRG1, maspin, and EMT markers to downregulate proliferation, invasion, and tumor growth of bladder carcinoma cells." (PMID 34662721, 2022). "CAPE attenuates proliferation, invasion, and growth of bladder carcinoma cells in vitro and in vivo, inducing the expressions of GDF15, NDRG1, and maspin via ERK, p38, or AMPKα1/2 signaling pathways." (PMID 34662721, 2022). "Ours has been the first study to reveal that arsenic can induce HO-1, NDRG1 and MT3 gene expressions in bladder carcinoma T24 cells." (PMID 30813460, 2019). "To further understand the mechanism by which NDRG1 mediates the development of bladder cancer, we assessed the expression levels of EMT-related markers after modulating NDRG1 expression in 5637 cells and T24 cells." (PMID 30914736, 2019). "In vitro studies demonstrated that over-expression of NDRG1 significantly decreased the proliferation rate of MCF7 breast and EJ bladder cancer cell lines." (PMID 26431493, 2015). "Our study is the first study to demonstrate the modulations of NDRG1, NDRG2, and NDRG3 gene expressions by GDF15 in bladder carcinoma cells." (PMID 26249737, 2015). "The expressions of mammary serine protease inhibitor (MASPIN) and N-myc downstream-regulated family genes (NDRG1, NDRG2, and NDRG3) were upregulated by GDF15 overexpressions and rhGDF15 treatments in bladder carcinoma cells." (PMID 26249737, 2015). "The effects of IL6 on the dysregulation of EMT markers and the expressions of MASPIN, NDRG1, and KAI1 genes in bladder carcinoma cells were examined." (PMID 23762858, 2013). "Our results suggest that the effects of interleukin-6 on the regulation of epithelial-mesenchymal transitions and the expressions of the MASPIN, NDRG1, and KAI1 genes attribute to the modulation of tumorigenesis in human bladder carcinoma cells." (PMID 23762858, 2013). "Moreover, downregulation of CA9, NDRG1, SLC2A1, VEGFA, and upregulation of MDM2 were further verified in an additional bladder cancer cell line, 5637 cells." (PMID 38339062, 2024). "Our results suggest that decreased expressions of NDRG1, NDRG2, and MASPIN genes may account for the increased cell proliferation and invasiveness in bladder carcinoma cells with MT3 stably overexpressed." (PMID 30813460, 2019). "The downregulation of NDRG1, NDRG2, and MASPIN gene expressions could account for the enhancement of proliferative and invasive functions of MT3 in bladder carcinoma cells." (PMID 30813460, 2019).
bladder cancer (continued). "Upregulations of MASPIN, NDRG1, NDRG2, and NDRG3 expressions may account for the antitumor characteristics of GDF15 in human bladder carcinoma cells." (PMID 26249737, 2015). "The elucidation of whether IL6 directly or indirectly affects EMT markers in bladder carcinoma cells by inducing of MASPIN and NDRG1 warrants further investigation." (PMID 23762858, 2013). "The dysregulation of the EMT and the altered MASPIN, NDRG1, and KAI1 gene expression induced by IL6 may lead to the modulation of tumorigenesis in bladder carcinoma cells." (PMID 23762858, 2013). "The functions and regulatory mechanisms of NDRG1 gene have not been conclusively evaluated in human bladder carcinoma cells." (PMID 23762858, 2013). "Moreover, reports indicate that NDRG1 is upregulated by HIF-1 and that the NDRG1 protein level could more accurately reflect tumour hypoxia than that of HIF-110,11, suggesting that NDRG1 may play a role in the development of bladder cancer and is a potential biomarker." (PMID 30914736, 2019). "Interestingly, our study is the first report which revealed that GDF15 blocked the effect of TGFβ/Smad signaling on the maspin and NDRG1 expressions in bladder carcinoma cells although GDF15 did not affect the phosphorylation of Smad 2/3 and Smad 1/5 in bladder carcinoma cells." (PMID 35884930, 2022).
lung carcinoma (17 papers, 2004 to 2026). "In lung cancer, increased NDRG1 expression is associated with resistance to chemotherapy and is linked to the cellular response to nickel, a known tumor driver in air pollution." (PMID 41725076, 2026). "In the work of Wang and collaborators, NDRG1 expression levels were determined in the serum of control and lung cancer patients using ELISA." (PMID 40332138, 2025). "Overexpression of NDRG1 significantly downregulated chemosensitivity to cisplatin in lung cancer A549 cells; at the same time, the author informs that overexpression of NDRG1 in lung cancer A549 cells significantly downregulated cisplatin-induced cytotoxicity." (PMID 37377864, 2023). "The overexpression of NDRG1 was induced by hypoxia in various human cancers, like lung cancer, liver cancer, and brain cancer." (PMID 34099022, 2021). "The increased expression of NDRG1 in response to Fe-deprivation in all the cell lines used in this investigation agreed with that previously observed in prostate and lung cancer cell lines." (PMID 26335183, 2015). "NDRG1 has been recently reported to predict tumor angiogenesis and poor outcome in patients with lung cancer." (PMID 24299561, 2013). "The rate of NDRG1 mutations was higher in the CDDP_EAGLE-1, EXCEPTIONAL_RESP, and TCGA-UCEC cohorts, including data from the Environment and Genetics in Lung Cancer Etiology study, patients with lasting clinical response, and uterine corpus endometrial carcinoma patients, respectively." (PMID 40332138, 2025). "Importantly, research found that NDRG1 promotes the stem-like properties of lung cancer cells through Skp2-mediated ubiquitination preventing the degradation of c-Myc." (PMID 34099022, 2021). "We also reported that NDRG1 knockdown induces decreased production of potent angiogenic factors and tumor angiogenesis by lung cancer cells, and also that NDRG1 is a predictive marker for tumor angiogenesis and poor prognosis in patients with no-small cell lung cancer." (PMID 22844455, 2012). "In contrast to Ndrg1, HIF-1α was present in both normal and lung cancer cells at similar levels." (PMID 15341671, 2004).
neuroblastoma (17 papers, 2012 to 2025). Neuroblastoma (NB) is the most common solid, extracranial childhood tumor. "The downregulation of NDRG1 mRNA expression has been shown to be associated with poor prognosis of neuroblastoma patients." (PMID 36160437, 2022). "NDRG1-overexpression in the c-Myc-overexpressing neuroblastoma cell line SK-N-MC caused reduced cell size and reduced colony formation, confirming the tumor-suppressive role of NDRG1." (PMID 31485792, 2019). "mRNA and protein expression were investigated in 48 tissue specimens from neuroblastoma patients, and low NDRG1 expression was significantly associated with prognostic factors such as primary tumor size, MYCN amplification, and poor prognosis." (PMID 31485792, 2019). "More recently, it has been reported that low levels of NDRG1 is associated with poor prognosis in neuroblastoma patients." (PMID 27894074, 2017). "In silico studies of neuroblastoma tumor samples revealed that low expression of NDRG1 was associated with poor survival." (PMID 27894074, 2017). "In addition, the neuroblastoma study revealed that NDRG1 is associated with increased level of resistant-related proteins such as MDR, LRP-1, and MRP-1." (PMID 29801473, 2018). "In addition, the neuroblastoma study revealed that overexpression of NDRG1 causes increased level of resistant-related proteins such as MDR, LRP-1, and MRP-1." (PMID 29801473, 2018). "Zhang and colleagues demonstrated that NDRG1 overexpression in KP-N-NS neuroblastoma cells resulted in a significant increase in cell viability relative to control cells in response to incubation with vincristine, cisplatin, teniposide, and epirubicin." (PMID 40378957, 2025). "In aggressive childhood cancer, neuroblastoma, NDRG1 is considered to be a tumor suppressor, with its low expression being significantly associated with prognostic factors such as primary tumor size, MYCN amplification, and poor prognosis." (PMID 40378957, 2025). "Marked upregulation of the metastasis suppressor N-myc downstream regulated gene-1 (NDRG1), which is known to be activated and upregulated by thiosemicarbazones in adult cancers, was also detected in thiosemicarbazone-treated neuroblastoma cells." (PMID 36160437, 2022). "We have previously demonstrated the upregulation of NDRG1 by thiosemicarbazones and the anticancer effects of NDRG1 in cancer cells derived from pediatric solid tumors, including neuroblastomas." (PMID 36160437, 2022). "Our initial results in a single neuroblastoma cell line also suggest that di-2-pyridylketone 4-cyclohexyl-4-methyl-3-thiosemicarbazone (DpC) can potently induce NDRG1 expression in these cells." (PMID 35008802, 2021). "After establishing the potency of DpC in inducing cell death, we focused on investigating its potency in upregulating NDRG1, a positive prognostic factor in neuroblastoma." (PMID 35008802, 2021). "While these findings indicate that NDRG1 plays a pivotal role in cellular lipid uptake in neuroblastoma, further investigation is needed to fully explain the exact mechanism of NDRG1 action." (PMID 35008802, 2021). "NDRG1-mediated effects are particularly intriguing, since NDRG1 has proved to be a promising positive prognostic factor in neuroblastoma." (PMID 35008802, 2021). "NDRG1 is repressed in cell lines with MYCN amplification and this down-regulation is known to be associated with MYCN effects in neuroblastomas." (PMID 29018329, 2017). "To further corroborate the mutually exclusive expression of NDRG1 and LSD1 we examined the relevance of NDRG1 in neuroblastoma patients." (PMID 27894074, 2017). "A study on NDRG1 expression in tumors obtained from neuroblastoma patients revealed its clinical significance with less expression being associated with tumor progression and poor survival." (PMID 29018329, 2017). "MYCN down-regulation by CDDO resulted in re-expression of NDRG1 which is otherwise known to be repressed in neuroblastoma." (PMID 29018329, 2017).
neuroblastoma (continued). "NDRG1 was originally identified as a major target gene repressed by the transcription factor MYCN (also named N-Myc) in neuroblastoma cells." (PMID 28981455, 2017). "Next, we analyzed LSD1 and NDRG1 expression in a microarray gene expression data of 59 NBs, of which 50 were neuroblastoma and 9 were ganglioblastoma and ganglioneuromas." (PMID 27894074, 2017). "In the current study, we demonstrated that LSD1 in cooperation with MYCN controls cell migration and invasiveness of neuroblastoma cells through transcription regulation of the metastatic suppressor NDRG1." (PMID 27894074, 2017). "Our in vitro findings imply that also in patients high LSD1 and low NDRG1 levels should be inversely correlated in metastatic Neuroblastomas." (PMID 27894074, 2017). "Collectively, these findings demonstrated that high levels of LSD1 and NDRG1 expression are mutually exclusive in neuroblastoma, and the expression levels of NDRG1 are significantly lower in MYCN-amplified tumors." (PMID 27894074, 2017). "This revealed a number of Akt-inhibitor-resistant lines displaying markedly elevated SGK1 that also exhibited significant phosphorylation of the SGK1 substrate NDRG1 [N-Myc (neuroblastoma-derived Myc) downstream-regulated gene 1]." (PMID 23581296, 2013). "Additionally, the upregulation of NDRG1 induces cell death in the Neuro2a mouse neuroblastoma cell line." (PMID 39444004, 2024). "However, its correlation with better prognoses and overall patient survival in neuroblastoma makes NDRG1 a target worth investigating in this pediatric malignancy." (PMID 35008802, 2021). "Schwann cells share a neural crest origin with neuroblastoma cells, thus indicating that NDRG1 could play a similar role in lipid metabolism in these cell types." (PMID 35008802, 2021). "Moreover, thiosemicarbazone treatment greatly increases NDRG1 levels, a positive prognostic factor in neuroblastoma." (PMID 35008802, 2021). "NDRG1 likely serves as a tumor suppressor in neuroblastoma development." (PMID 31485792, 2019). "Moreover these data strongly suggest that NDRG1 can be used as marker of neuroblastoma differentiation in vivo." (PMID 27894074, 2017). "MYCN is known to negatively regulate NMYC downstream-regulated gene 1 (NDRG1) in neuroblastomas." (PMID 29018329, 2017). "In summary, our findings uncover a previously unidentified model in the control of EMT, suggesting that MYCN/LSD1 inhibition de-represses NDRG1 expression, thereby inducing an NDRG1-dependent inhibitory effect on cell migration and invasiveness of neuroblastoma cells." (PMID 27894074, 2017). "The exact role of NDRG1 and family members in cancers including neuroblastoma remain to be fully elucidated, however the iron chelator Dp44mT which exhibits anti-cancer properties has been reported to upregulate the expression of NDRG1." (PMID 23226679, 2012). "Furthermore, DpC succeeded in downregulating total EGFR and phosphorylation of its most prominent tyrosine residues through the involvement of NDRG1, a positive prognostic marker in neuroblastoma, which was markedly upregulated after thiosemicarbazone treatment." (PMID 35008802, 2021). "Here, we therefore aimed to investigate the molecular effects of DpC on a panel of neuroblastoma cell lines to evaluate its impact on some of the most prominent molecules (MYC oncoproteins, NDRG1, and EGFR) in neuroblastoma." (PMID 35008802, 2021). "NDRG1 expression in neuroblastoma cells can also be induced by the transcription factor forkhead box D3 (FOXD3), which has a lower expression in neuroblastoma tissues and cell lines (SH-SY5Y and SK-N-SH)." (PMID 31485792, 2019). "Although IIF induced a significant increase in mRNA NDRG1 expression and EGFR (mRNA, total protein, and p1068EGFR) decreased, the real meaning and role of EGFR activity in neuroblastoma require further investigation." (PMID 30135355, 2018). "The relative expression levels of NDRG1, LSD1 and MYCN were further analyzed in neuroblastoma patients." (PMID 27894074, 2017).